MMP9 (matrix metallopeptidase 9)
Diseases named in the same sentence as MMP9 in open-access papers (continued):
Sharing a sentence is not in itself a finding about the gene and the disease.
prostate carcinoma (continued). "It has been indicated that MMP-9 enhances prostate cancer cell invasion by specifically degrading serpin protease nexin-1 (PN-1) and deregulating the inhibitory effect of PN-1 on urokinase plasminogen activator (uPA)." (PMID 40160822, 2025). "Another study revealed that L-theanine treatment reverses MMP9-mediated metastasis in prostate cancer by downregulating Snail and MMP9 expression." (PMID 39990676, 2025). "A study of prostate cancer has revealed the molecular mechanism by which MMP-9 regulates tumor cell invasion and metastasis." (PMID 40160822, 2025). "MMP-9 activity is observed in many metastatic tumors, such as breast, esophageal, gastric, and prostate cancers." (PMID 41273852, 2025). "A pre-metastatic conditioning study using exosomes derived from hypoxic prostate cancer cells revealed the highest MMP (MMP9 and MMP2) activity in prostate cancer target metastatic organs, such as the liver, kidney, and spleen." (PMID 41463352, 2025). "Catechins and flavonoids suppress prostate cancer progression by inhibiting Akt/NF-κB/MMP-9 signaling." (PMID 41346617, 2025). "The involvement of CBP in the survival and invasion of prostate cancer cells through the mediation of MMP9 transcription has been documented." (PMID 39343952, 2024). "It has been reported that AHR activation in gastric and prostate cancer cells induces MMP-9 upregulation." (PMID 39125717, 2024). "Similar downregulation of MMP-2 and MMP-9 levels has been observed in prostatic carcinoma by inhibiting the signaling of JNK, PI3K, Akt to reduce NF-κB and AP-1 DNA-binding activities." (PMID 38611849, 2024). "In prostate cancer tumor models, vitamin D treatment was reported to downregulate MMP-9 and IL-8 levels, as well as inhibit the migration and tube formation in human umbilical vein endothelial cells (HUVECs)." (PMID 39335182, 2024). "In this case, the gelatinolytic activity of metalloproteases 2 (MMP2) and 9 (MMP9) is assessed by zymography, as they are the MMPs most involved in the progression of prostate cancer." (PMID 39456984, 2024). "Our study shows that TN-EA, daidzein, and genistein reduce N-cadherin expression, consistent with previous reports indicating that genistein and daidzein inhibit breast and prostate cancer invasion by regulating MMP-9 expression and the EMT process." (PMID 39273231, 2024). "Still, they also found that the phosphorylation of genes like FAK reduced metalloproteases (MMP2 and MMP9), decreasing breast and prostate cancer cell invasion by promoting PIK-Akt pathway activity and keeping Nf-kB in the cytoplasm of the cancer cell." (PMID 39063176, 2024). "MMP-7 and MMP-9 are known to be markers of prostate cancer invasion, and we observed elevated expression of these proteins." (PMID 38511770, 2024). "Patients with prostate cancer can increase the expression of MMP-9 in their peripheral blood NK cells and secrete factors that recruit and polarize monocytes." (PMID 39712025, 2024). "The anti-angiogenic activity of genistein is also investigated in prostate cancer, where it downregulates the genes level of uPAR, MMP-9, VEGF, neuropilin, TSP-1, TSP, TGF-β2, BPGF, PAR-2, protease M, and LPA." (PMID 38611849, 2024). "The invasion of prostate cancer was reduced by vitamin D through the reduction in MMP-9 and cathepsins secretion, while MMP-1 (a tissue inhibitor) was activated." (PMID 39335182, 2024). "A more recent study showed that ASA suppressed the invasion of prostate cancer cells by inhibiting MMP-9 activity." (PMID 38792627, 2024). "Mangiferin (200 μM) suppressed the TNF-α-induced expression of MMP-9 by inhibiting the transcription factor NF-κB in prostate cancer cells." (PMID 38540096, 2024). "The stimulus of experimental cells with TNF-α enhanced the Matrix metallopeptidase 9 activity in prostate cancer cells." (PMID 38137424, 2023).
prostate carcinoma (continued). "PEITC also promoted the suppression of the expression of MMP2 and MMP9 proteins, which in turn attenuated tumor invasion and cell migration in prostate cancer cells." (PMID 36765652, 2023). "Our group confirmed that exposure of PC3 cells to resistin increases the secretion level of MMP-2 and MMP-9 in the conditioned medium, favoring invasion in prostate cancer cells." (PMID 38137922, 2023). "PEITC-mediated up-regulation of miR-194 was due to the reduced expression of MMP-2 and MMP-9 through targeting BMP1 in prostate cancer cells." (PMID 36765652, 2023). "In prostate cancer, their roles have been discussed in a recent systematic-like review, where special emphasis is placed on MMP2, MMP7, and MMP9 since they are the most studied and most often positively correlated with prostate cancer tumorigenicity." (PMID 38255186, 2023). "The release of mature epiregulin occurs via proteolytic cleavage by ADAM17, MMP2, and MMP9 which are increased in castration-resistant prostate cancer cells." (PMID 36994208, 2023). "CXCL12 (SDF-1)/CXCR4 interactions play an essential role in prostate cancer migration and invasion to the bone by activating Akt1 and MMP-9 expressions." (PMID 36863017, 2023). "The result based on prostate cancer showed that mangiferin inverted TNF-α-induced mRNA as well as MMP-9 expression." (PMID 38137424, 2023). "The resulting hydrolysate fractions were investigated for their antimicrobial and cytotoxic activities, including the expression of gelatinases mmp-2 and mmp-9 in human prostate cancer cell lines (PC3)." (PMID 37704667, 2023). "In the present study, we identified a novel role of IRS-2 in promoting the secretion of MMP-9, which causes activation of the IGF signaling pathway in human prostate cancer cells, PC3." (PMID 37894751, 2023). "It has been reported that the siRNA-mediated knockdown of MMP-9, uPAR, and CB inhibits the invasiveness and migration of prostate cancer cells and leads to apoptosis, both in vitro and in vivo." (PMID 35723293, 2022). "Our results indicated that the sonicated extract suppresses prostate cancer cell migration via the regulation of MMP-9 and TIMP-1." (PMID 36605288, 2022). "SENP1 is linked to prostate cancer progression because SENP1 regulation of matrix metallopeptidase 2 (MMP2) and matrix metallopeptidase 9 (MMP9) through the hypoxia-inducible factor 1-alpha (HIF-1α) signaling pathway promotes progression." (PMID 35408841, 2022). "As anti-cancer agent, rubimaillin suppresses Notch signaling to down-regulate MMP-2 and MMP-9 expressions in inhibiting growth and invasion of prostate cancer cells." (PMID 35773731, 2022). "Anti-cancer activity of quercetin such as induction of apoptosis, fatty acid synthase (FAS), inhibition of cell proliferation, reduction of metalloproteinase-2 (MMP-2), and metalloproteinase-9 (MMP-9) expression in prostate cancer cells were studied." (PMID 35971151, 2022). "ADAM17 targets MMP2 and MMP-9 via EGFR-MEK-ERK pathway activation to promote prostate cancer cell invasion." (PMID 36172139, 2022). "The differential expression within the prostate cancer pathway in PAC cell lines was mostly focused on MMP9 and the group of growth factors and their receptors (GFR), also known as RTK." (PMID 35109825, 2022). "Notch1 can promote expression levels of MMP-2 and MMP-9 in increasing progression and metastasis of prostate cancer cells." (PMID 35773731, 2022). "Matrix metalloproteinase-9 (MMP-9) was selected because it is an important enzyme used in prostate cancer cell migration and invasion." (PMID 36605288, 2022). "MMP-9 participates in tumor metastasis in several tumor cancers, including lung cancer, cervical cancer, and prostate cancer." (PMID 36605288, 2022). "When prostate cancer cell metastases to the bone, the cancer cell secrete matrix metalloproteinase-9 (MMP-9), urokinase plasminogen activator receptor (uPAR), and cathepsin B (CB), which degrade the bone matrix to release growth factors." (PMID 35812177, 2022).
prostate carcinoma (continued). "Generally, proteolytic degradation of extra-cellular matrix (ECM) is mediated by MMPs, with MMP-2 and MMP-9 playing a critical role in prostate cancer progression." (PMID 36497399, 2022). "In prostate cancer, infiltrating MCs can reduce androgen receptor (AR) transcription and increase the aggressiveness of prostate cancer cells by increasing MMP9 expression." (PMID 36591235, 2022). "We found that most patients with prostate cancer overexpressed MMP-9; on the other hand, most of them underexpressed TIMP-1, RECK, and miR-338-3p." (PMID 35097136, 2021). "The osteogenic protein BMP-7 and endopeptidase MMP-9 are upregulated in both breast and prostate cancer bone metastases." (PMID 34440874, 2021). "Approximately 58% of the patients with prostate cancer presented MMP9 upregulation, while 73%, 65%, and 69% downregulated IMP-1, RECK, and miR-338-3p, respectively." (PMID 35097136, 2021). "In vivo the MC-stabilizer cromolyn and levetiracetam have comparable effect in restraining T1525-prostate cancer tumors, which strictly depend on MCs provision of MMP9 for their growth." (PMID 33737929, 2021). "A positive correlation was noticed between DPP4/CD26 and MMP9 dosage in 40% pSS saliva samples, a connection that has already been reported in prostate cancer." (PMID 34220840, 2021). "Following the curcumin treatment in a xenograft model of prostatic cancer, MMP-9 and MMP-2 expression remarkably decreased." (PMID 34456716, 2021). "For instance, blocking the PI3K/AKT axis in prostate cancer cells by the administration of the PI3K inhibitor ZSTK474 prevents bone metastasis in vivo via downregulation of the pro-invasive MMP9." (PMID 34064589, 2021). "This study aimed to evaluate the application of MMP-9 and its regulators (TIMP-1, RECK, and miR-338-3p) as diagnostic and prognostic indicators of prostate cancer." (PMID 35097136, 2021). "It is well established that increased expression of MMP-2 and MMP-9 have been evaluated as prognostic marker in BC and prostate cancer." (PMID 34315513, 2021). "Using a human acute monocytic leukemia cell line, we revealed that miconazole impairs the expression of chemokines and MMP-9 induced by 27OHChol, which promotes the proliferation of breast and prostate cancer cells." (PMID 34744703, 2021). "FGF11-miR-541 activity in response to T-cell infiltration in prostate cancer contributes to prostate cancer cell invasion, likely through suppression of androgen receptor and matrix metallopeptidase 9 (MMP9) activity." (PMID 34068954, 2021). "The stromal-cell–secreted MMPs play an indispensable role in cancer cell metastasis, with MMP-2 and MMP-9 being the best-studied MMPs in prostate cancer metastasis." (PMID 33535458, 2021). "For instance, AKT promotes the secretion of pro-invasive MMPs, especially MMP9, in breast as well as prostate cancer cells." (PMID 34064589, 2021). "For instance, the co-culture of preadipocytes suppresses AR expression through the up-regulation of miR-301a expression in prostate cancer cells, resulting in the up-regulation of TGFβ1, Smad, and MMP9 expression for metastasis." (PMID 32971847, 2020). "A previous report demonstrated consistently that increased infiltration of Pref-1 and CD29 positive preadipocytes promote prostate cancer metastasis via the mR301a/AR/TGFβ1/Smad/MMP9 pathway." (PMID 32971847, 2020). "Over-expression of TRPV2 in androgen-dependent LNCaP prostate cancer cells led to the induction of invasive markers, matrix metalloproteinases (MMP9) and cathepsin-B." (PMID 32825277, 2020). "SENP1 can regulate MMP-2 and MMP-9 through the HIF1α signaling pathway, thereby promoting the progression of prostate cancer cell lines and bone metastasis." (PMID 33123273, 2020). "In a study in prostate cancer cell lines, MMP9 expression increased after aryl hydrocarbon exposure, events which were suggested to facilitate tumor invasion." (PMID 33488929, 2020).
prostate carcinoma (continued). "Consist with the previous study, treatment with downregulation of DKK-3 facilitated malignant phenotypes of prostate cancer cells, upregulating MMP-2 and MMP-9, and even reversed the effect caused by overexpression of LINC00261." (PMID 33013201, 2020). "miR146a has been shown to inhibit MMP2 expression in prostate cancer tissue 80 and the activity of MMP9 in human cardiac cells." (PMID 31183875, 2020). "The interaction of CD44, a cell surface adhesion receptor, and matrix metalloproteinase 9 (MMP9) results in secretion of active MMP9 leading to migration and invasion of prostate cancer cells." (PMID 31358880, 2019). "MMP9 was positioned predominantly in Gleason score 6 and 7 prostate cancers, making it unclear how specific these positioning patterns are more generally to the different Gleason scores subgroups." (PMID 31681438, 2019). "Studies have shown overexpression of IL24 in TRAMP mice, possibly interleukin promotes initial steps of prostate cancer progression by upregulating genes such as matrix metallopeptidase 9, (MMP9) via the JAK-STAT signaling pathway." (PMID 30972102, 2019). "Increased MMP-9 expression is known to correlate to more advanced prostate cancer in human patients." (PMID 31391540, 2019). "EGCG (20 μM) reduce the activity of MMP-2 and MMP-9 in prostate cancer cells and decrease the expression of MMP-9 in bladder cancer cells." (PMID 31781485, 2019). "Our results highlight the capability of ALCAR to down-modulate growth, adhesion, migration and invasion of prostate cancer cells, by reducing the production of several crucial chemokines, cytokines and MMP9." (PMID 31718684, 2019). "Another study revealed that the knockdown of endothelial cell specific molecule-1 promoted tumorigenicity and metastasis through the regulation of MMP2/MMP9 in prostate cancer cells." (PMID 31777601, 2019). "In the case of mouse models for bone metastasis with prostate cancer cells, genistein reduced the level of MMP-9, while in an orthotopic model of prostate cancer it inhibited metastasis to lymph nodes and lungs." (PMID 30823649, 2019). "In prostate cancer, Notch1 silence inhibits invasion through matrix metalloproteinase-9 (MMP9) and urokinase plasminogen activator (uPA)." (PMID 31477177, 2019). "RUNX2 and MMP-9 are considered as markers of breast and prostate cancer cells, which metastasize to bone." (PMID 31331331, 2019). "It has revealed that MMP2 and MMP9 are correlated with the invasive and metastatic phenotypes of prostate cancer cells." (PMID 29300772, 2018). "Our results demonstrated for the first time that the S100A4-embigin/AMPK/mTORC1/p21WAF1 and NF-κB/MMP9 axis is a vital oncogenic molecular cascade for prostate cancer progression." (PMID 30041429, 2018). "IL8 is not only capable of stimulating growth, MMP9 secretion, and invasivity of the epithelial prostate cancer cells in vitro, but also of promoting metastasis marked by MMP9 production and enhanced neovascularity." (PMID 29921791, 2018). "The potential roles of IGFs and IGFBPs in mediating cell movement and migration have been studied more so in cancer cells than in stromal stem cells, for, for example, degradation of IGF‐1/IGFBP3 complex by MMP‐9‐triggered prostate cancer cell migration." (PMID 29321953, 2018). "In orthotopic xenograft transplantation systems of human fibrosarcoma and prostate carcinoma cell lines, tumor-recruited neutrophils release MMP9 that remodels the ECM to induce angiogenesis and promote metastasis." (PMID 30356678, 2018). "We propose that the S100A4-embigin/AMPK/mTORC1/p21WAF1 and NF-κB/MMP9 axis is a vital oncogenic molecular machinery exploited by a certain fraction of prostate cancers for progression." (PMID 30041429, 2018). "Our findings confirm that Ang1–7 can also modulate the activity of both gelatinases A and B in prostate cancer cells, that MMP-9 activity was upregulated in DU-145 and downregulated in PC3, and that MMP-2 levels were suppressed in LNCaP and PC3 cells." (PMID 30361641, 2018).
prostate carcinoma (continued). "In this study, we investigated the clinical importance and link between AR, EGFR and MMP-9 in prostate cancer by using clinical tissues from prostate cancer patients and prostate cancer cell lines." (PMID 30134822, 2018). "Our results showed that embigin induces prostate cancer cells migration and activation of NF-κB, and MMP9 activation and that the migration was enhanced by extracellular S100A4." (PMID 30041429, 2018). "In particular, expression and activity of gelatinases, MMP-2 (72 kDa) and MMP-9 (92 kDa) have been shown to be significantly up-regulated in a variety of cancers, including prostate cancer." (PMID 30197761, 2018). "Elevated levels of MMP-2 and MMP-9 are observed in prostate cancer and correlate with increased metastasis." (PMID 28257035, 2017). "1,25D3 reduces prostate cancer cell invasion by suppressing the expression of MMP-9 and cathepsins and promoting the activity of tissue inhibitors of metalloproteinase-1 (TIMP-1)." (PMID 28947955, 2017). "As the member of MMPs family, the role of MMP-2 and MMP-9 in prostate cancer has been extensively studied, there are still multiple evidence that shed light on the MMPs and their impact on ovarian cancers." (PMID 28476025, 2017). "In a mouse model, mast cells enhanced prostate cancer growth via modulation of androgen receptor and increasing MMP-9 expression." (PMID 28446910, 2017). "Several evidences indicated that CXCR4/SDF1 promoted prostate cancer cell invasion through MMP9 activation." (PMID 29108247, 2017). "Knockdown of MARCKS reduced migration and invasion of prostate cancer cells, reduced MMP9 mRNA expression, as well as decreasing cell spreading and increased cell:cell adhesion in prostate cancer cell colonies." (PMID 29069765, 2017). "The interaction of CD44 and proteolytic form of MMP-9 is particularly involved in the invasion of prostate cancer cells (PC3) derived from bone metastases." (PMID 28326306, 2017). "Mast cells were pro-tumorigenic in the initial stages of prostate cancer by supplying MMP-9 in the microenvironment, but became dispensable at later stages." (PMID 28446910, 2017). "The levels of MMP‐2 and MMP‐9 expression are considered biomarkers for judging the malignancy of prostate cancer progression and evaluating therapeutic effects." (PMID 28846829, 2017). "Other studies show that 1,25D3 inhibits prostate cancer cell adhesion, migration and invasion by various mechanisms such as up-regulation of E-cadherin, down-regulation of integrins, MMP-9 and cathepsins, DICKKOPF-4 or protein kinase A." (PMID 28947955, 2017). "The balance between MMP-9 and TIMP-1 are reported to play a critical role of migration and invasion by stimulating degradation of the ECM in prostate cancer cell and is associated with enhanced tumor metastatic potential." (PMID 28108731, 2017). "Other studies have also reported the overexpression of IL8 in human prostate cancer cells, with concomitant upregulation of MMP9 and collagenase activities." (PMID 29164058, 2017). "Quercetin has been proved to downregulate MMP-2 and MMP-9 protein expression in prostate cancer cells." (PMID 28811592, 2017). "In prostate cancer, RUNX2 was associated with skeletal destruction by enhancing the expression of metastasis-related proteins MMP9 and MMP13." (PMID 27007162, 2016). "In conclusion, our study provides evidence that SFMBT2 regulates prostate cancer metastasis either by direct repression of YY1 target genes such as MMP-9, MMP-26, and N-CoR and by indirect regulation of MMP-2, MMP-3, and KAI1 gene expression." (PMID 27340776, 2016). "Knockdown of SFMBT2 increases prostate cancer cell migration and invasion via direct repression of target genes such as MMP-9, MMP-26, and N-CoR in LNCaP and VCaP cells." (PMID 27340776, 2016). "Recently, MMP-9 upregulation has been documented in several human cancers, including prostate cancer, ovarian cancer, and hepatocellular carcinoma." (PMID 26716898, 2016).